CCND1 (cyclin D1)
Diseases named in the same sentence as CCND1 in open-access papers (continued):
Sharing a sentence is not in itself a finding about the gene and the disease.
cancer (continued). "Hence, we aimed to investigate the role of CCND1 polymorphism G870A (rs9344) in overall cancer susceptibility amongst Indian population by conducting this meta-analysis." (PMID 30361291, 2018). "Given that cyclin D1 is thought to be a collaborative oncogene, and the DNA repair defects often are associated with predisposition to cancer, it was considered “surprising, that this protein also mediates the repair of damaged DNA, a mechanism that commonly prevents cancer”." (PMID 29137223, 2017). "Further studies supported the notion that PCA-induced Cyclin D1 inhibition may subsequently cause cell cycle arrest and apoptosis of various human cancer cells." (PMID 29285297, 2017). "Of the SNPs in CCND1, the mutation is the common and the some allele changes do lead to an alternatively spliced transcript of CCND1, which facilitates the passage of the variant cell through the G1-S checkpoint and rapid proliferation, ultimately resulting in cancer development." (PMID 29113352, 2017). "The cyclin D1 proto-oncoprotein is a crucial regulator in cell-cycle progression, and aberrant overexpression of cyclin D1 is linked to tumorigenesis of many different cancer types." (PMID 28877265, 2017). "Cyclin D1 transformed hTERT human fibroblast to a cancer-associated fibroblast phenotype." (PMID 29137220, 2017). "Cyclin D1 is encoded by the CCND1 gene in human and is overexpressed in many cancers." (PMID 27095572, 2016). "Importantly, aberrant cyclin D1 overexpression is closely linked to cancer development, progression, poor prognosis, and chemoresistance, thus highlighting cyclin D1 as an attractive drug target." (PMID 28035994, 2016). "Aberrant cyclin D1 expression has been associated to several types of cancers." (PMID 27816050, 2016). "Previous studies suggest that Cyclin D1 may regulate cell adhesion and migration but the mechanisms underlying such regulation and the relevance to cancer development are unknown." (PMID 27181366, 2016). "The germline sequence variants of this gene have been investigated by numerous studies of various cancers, and have indicated that the common polymorphism that alters splicing of the cyclin D1 transcript may also have an effect on the cancer risk and outcome." (PMID 25436006, 2015). "The evidence indicates that common single nucleotide polymorphisms (SNPs), which are known to alter the splicing of the cyclin D1 transcript, may modify the action of cyclin D1 in cancer cells and affect the cancer risk and outcome." (PMID 25436006, 2015). "CCND1, a key regulatory protein, plays an important role in the transition from the G1 to S phase of the cell cycle, and its deregulation has been implicated in the pathogenesis of several types of cancers." (PMID 25888980, 2015). "Activation of the RAS-MEK-ERK pathway, along with ERBB2 in hormonal-driven cancers (such as breast) and the Wnt pathway have also been associated with higher CCND1 expression, that may occur through increasing its transcription." (PMID 25596748, 2015). "Because CCND1 is an important regulator of cell cycle progression and can function as a transcriptional coregulator, overexpression of CCND1 and deregulation of CCND1 degradation are thought to be associated with the development and progression of cancer [7–11 and references therein]." (PMID 26172301, 2015). "Several observations have suggested that inactivation of RB in the genome or in the phenotype can lead to abnormal expression of p16INK4a or cyclin D1, and promote cell cycle G1-S transition, resulting in sensitivity to loss of inhibition by ERα in cancer cells." (PMID 24559156, 2014). "In addition, cyclin D1 over-expression is usually an early event in carcinogenesis and a prognostic indicator associated with poor survival in cancers." (PMID 25514243, 2014). "In oral SCC, there is a possibility that the expression of cyclin D1 may be associated with proliferation of a cancer cell, based on an association with Ki-67 expression." (PMID 24944679, 2014).
cancer (continued). "The association between CCND1 G870A polymorphism and cancer risk has been widely assessed." (PMID 25409185, 2014). "In addition to the association between cyclin D1 expression and human cancer, overexpression of cyclin D1 is tumorigenic, as supported by evidence that MMTV-driven cyclin D1 is sufficient for mammary hyperplasia and carcinoma development in transgenic mice." (PMID 23786849, 2013). "Even more importantly, the existence of cancer-specific splicing variants of key genes, such as the AR or CCND1 in PCa, might offer a therapeutic opportunity for targeting proteins that are not expressed in healthy cells." (PMID 23983695, 2013). "Evidence suggests that the CCND1 polymorphism may have a correlation with its overexpression in cancers." (PMID 23170138, 2012). "The response to tamoxifen was tested at two different ages (four and ten months of age) to test if tamoxifen could cause regression of preneoplasia and cancer initiated by over-expression of ERα and cyclin D1 either alone or in combination." (PMID 24575359, 2012). "Furthermore, Myc (c-myc), Ccnd1 (cyclin D1), and Cdkn1a (p21/Waf1) are Notch target genes implicated in cancer." (PMID 22720165, 2012). "Cyclin D1 was overexpressed in a variety of cancers and associated with cancer cell proliferation." (PMID 22666376, 2012). "Evidence implicates cyclin D1 (CCND1) G870A polymorphisms as risk factors for various cancers." (PMID 23170138, 2012). "Furthermore, one study demonstrated that the G870A and G1722C polymorphisms of cyclin D1 were in linkage disequilibrium in carcinomas of the head and neck." (PMID 22606291, 2012). "Cyclin D1 overexpression has also been linked to the development and progression of cancer." (PMID 21347286, 2011). "Cyclin D1 overexpression has been linked to the development and progression of cancer." (PMID 21347286, 2011). "The molecular mechanism of SHetA2 induction of apoptosis in cancer cells is associated with decreases in Bcl-2 and Bcl-xl levels, while G1 cell cycle arrest is associated with decrease of Cyclin D1 levels and induction of differentiation is associated with increase of E-Cadherin expression." (PMID 19784388, 2008). "Furthermore, mutations targeting SCFFbx4-αB crystallin in human cancers implicate ligase function in cyclin D1 overexpression and subsequent nuclear accumulation of active cyclin D1/CDK4 complexes." (PMID 18764945, 2008). "The overexpression of cyclin D1 has been linked to the development and progression of cancer." (PMID 17407548, 2007). "Several genes encoding protein products that are important in cancer and have functions related to cell cycle, growth, DNA replication and protein translation (such as CCND1, TOP2A, TOPBP1, TFRC; three members of H4 histone family [HIST1H4C, HIST1H4B, and HIST1H4E]; and EIF4G1)." (PMID 17498291, 2007). "Consequently, our findings may have broader implications for other HR-proficient cancers exhibiting concurrent cyclin D1 overexpression and ATM deficiency and suggest a biomarker-driven approach for the development of inhibitors of POLΘ." (PMID 40608419, 2025). "CCND1 expression was found to differ significantly between normal and malignant tissues in all stages of COAD, ESCA, KIRC, READ, STAD, and THCA, according to our pan-cancer research, suggesting that CCND1 may be used as a diagnostic biomarker in these types of cancer." (PMID 39188436, 2024).
cancer (continued). "CCND1 gene and its protein CyclinD1 are often changed by different molecular mechanisms, including amplification, chromosome translocation, mutation and activation of CyclinD1 expression pathways, which are essential in the occurrence and development of human cancer and aging." (PMID 37794858, 2023). "However, overexpression of CCND1 has been linked to drug resistance in cancer cells." (PMID 37744271, 2023). "Additionally, the common polymorphic variant A870 in the CCND1 gene may be a risk factor of cancer transformation." (PMID 35626215, 2022). "Thus, it can be suggested that any change in Cyclin D1 interaction with these proteins may change its associated pathway which can lead to onset of cancer." (PMID 33438725, 2021). "As shown with other regulators of the epithelial–mesenchymal phenomenon, expression of brachyury in carcinoma cells associates with a significant reduction in cell proliferation, whereby brachyury expression inversely correlates with the expression of phosphorylated Rb, Cyclin D1, and p21." (PMID 29774202, 2018). "Given that cyclin D1 is the most widely expressed cyclin D in different cell types and is most frequently implicated as a cancer driver in solid tumors, we hypothesize that, in many clinical settings, activation of CDK6 may be enhanced by the assembly function of p21CIP1 or p27KIP1." (PMID 29091774, 2017). "Thus, because the abnormal function of the CDK4-cyclin D1 protein complex might play a vital role in causing cancer, CDK4 can be considered a genetically validated therapeutic target." (PMID 26252490, 2015). "Therefore, the down-regulation of cyclin D1 by resibufogenin may be also useful to overcome the resistance of MEK inhibitor in malignant tumors with mutations in both KRAS and PIK3CA." (PMID 26121043, 2015). "The CCND1 G870A polymorphism will change the spliced transcript of CCND1 and lead to over expression of CCND1, which may lead to abnormal cell proliferation and contribute to cancer development." (PMID 25409185, 2014). "Finally, and most importantly, whether the CCND1 G870A polymorphism is independently predictive of cancer risk remains controversial." (PMID 24222746, 2013). "Finally and mostly importantly, whether the CCND1 G870A polymorphism is independently predictive of cancer risk remains controversial." (PMID 22606291, 2012). "A recent study showed the deregulation of cyclin D1 expression could directly lead to some of the hallmarks of cancer by causing proliferation, and this could be a mechanism-based targeted therapy to treat human cancers." (PMID 22949827, 2012). "Therefore, delineating the mechanism underlying nuclear cyclin D1-driven transformation is critical for understanding the role of cyclin D1 in tumorigenesis and development of therapeutic strategies for treatment of cancers overexpressing this protein." (PMID 18764945, 2008). "As cyclin D1 overexpression in human cancer has been postulated to occur through the loss of degradation machinery, the identification of the SCFFbx4/alphaB-crystallin ligase will allow new experimental approaches that address mechanisms of cyclin D1 overexpression in human cancer." (PMID 17224055, 2007). "Additionally, a polymorphism in the cyclin D1 locus that may affect splicing has been implicated in increased cancer risk or poor outcome." (PMID 16863592, 2006). "Umbelliferone—another naturally occurring coumarin—inhibits the release of cyclin D1, hindering its overexpression which can lead to cancer development." (PMID 41596223, 2026). "Extensive research has highlighted the pivotal role of Cyclin D1 in promoting cancer cell invasion and metastasis through the regulation of pathways associated with cell motility and tissue invasion." (PMID 41491194, 2026). "Cyclin D1 is pivotal in cell cycle progression and is often upregulated in various tumor types, driving cancer advancement." (PMID 41574218, 2026).
cancer (continued). "Cyclin D1 is uniquely overexpressed in solid tumors and promotes cancer progression through transcriptional regulation, maintenance of chromosomal stability, and modulation of cell migration." (PMID 41596432, 2026). "This STAT3 ODN-decoy has been tested in various cancer cell lines, where it displayed promising effects, such as apoptosis induction, diminution of cancer cell proliferation, and reduction in Bcl-xL and cyclin D1 gene expression." (PMID 41031165, 2025). "The abnormal expression of cell cycle regulatory proteins, particularly Cyclin D1 and CDK4/6, has often been linked to the onset of different types of cancers." (PMID 40510359, 2025). "Targeting the DDB1–AMBRA1–cyclin D1 complex for cancer therapy offers promising strategies to enhance the degradation of cyclin D1." (PMID 40408472, 2025). "Cyclin D1 overexpression in cancer induces replication stress and DNA damage, forcing cells to rely on specific repair pathways that can be targeted for therapy." (PMID 40608419, 2025). "NSD2 has been shown to play a role in cancer progression by regulating key oncogenes, such as cyclin D1 (CCND1), MYC proto‐oncogene, BHLH transcription factor (MYC), and BCL2 apoptosis regulator (BCL2), which contribute to cell survival and proliferation." (PMID 40386826, 2025). "MicroRNA-28-5p downregulates CCND1 (cyclin D1), a cell cycle regulatory protein considered a proto-oncogene, where overexpression is characteristic of cancer cells." (PMID 40563399, 2025). "It targets CREPT and RNAPII activity and the transcription of MYC, cyclin D1, and other oncogenes that are involved in cancer progression." (PMID 40723282, 2025). "Immunohistochemistry (IHC) analysis on the tissue microarray also revealed significant CCND1 protein overexpression in cancer samples versus normal, with high CCND1 expression in 52.2% of cancerous tissues versus 5% in adjacent para‐carcinoma tissues." (PMID 40145254, 2025). "The Cyclin D1 gene is regarded as the oncogene, the amplifications of which have been detected in cancers of various organs." (PMID 40224178, 2025). "Key cancer-related substrates include the proto-oncogene c-Myc, HIF1α (which promotes angiogenesis and migration), c-Fos (which activates CCND1 transcription to produce cyclin D1), and matrix metalloproteinases (MMPs) that facilitate invasion." (PMID 40424719, 2025). "Amplification of the gene and overexpression of cyclin D1 protein have frequently been found in several types of human malignant neoplasms." (PMID 40868982, 2025). "The overexpression of cyclin D1 has been widely reported in various cancers, including breast, lung, colon, and head and neck cancers." (PMID 39948552, 2025). "Overall, our findings reveal the critical role of circFOXK2 in stabilizing the oncogene CCND1 and promoting cancer progression, positioning circFOXK2 as a potential therapeutic target for ER-positive breast cancer in clinical settings." (PMID 40233410, 2025). "Cyclin D1, also referenced as CCND1, is a member of the Cyclin family and plays a prominent role in regulating cell division, adhesion and invasion in cancer progression." (PMID 41465166, 2025). "Twelve DEPs were identified to be involved in pathways in cancer and three DEPs (CCND1, Fosl1, Frizzled) were related to the Wnt signaling pathway." (PMID 41184253, 2025). "Overall, our results suggest that the relative balance between c-Myc and cyclin D1 activities offers valuable quantitative insights into the varying sensitivities of cancer cells to CDK4is." (PMID 41161384, 2025).
cancer (continued). "CME significantly reduced Cyclin D1 expression, resulting in cell cycle arrest in the G0/G1 phase, which inhibited the growth of cancer cells." (PMID 39803233, 2025). "Although cyclin D1 is known to drive cells to enter the S phase and initiate DNA replication, little is known about how cancer cells adapt to the resultant RS." (PMID 40608419, 2025). "In particular, overexpression of cyclin D1 and CDK4/6 is common in cellular transformation toward cancer and has been linked to the dysregulation of oncogenes." (PMID 40723282, 2025). "A recent study suggested that oncogene CCND1 was amplified in breast cancer through ecDNA formed by translocations.The amplification mechanism allows cancers to evade therapies targeting oncogenes maintained on ecDNA." (PMID 40702169, 2025). "On the one hand, β-catenin promotes cancer cell proliferation and migration by inducing c-myc, cyclin D1, and MMPs expression." (PMID 39901136, 2025). "Inhibition of p38 MAPK during this transition lead to a downregulation of cyclin D1 levels, slowing the conversion from G1 to S phase, thereby impeding cancer cell cycle progression and reducing cancer incidence." (PMID 40129568, 2025). "Overexpression of Cyclin D1 is commonly observed in various cancers, where it accelerates cell cycle progression and contributes to tumorigenesis." (PMID 40224178, 2025). "Overexpression of cyclin D1 is common in many cancers, where it can lead to uncontrolled cell cycle progression by passing the normal checkpoints that prevent the proliferation of damaged or mutated cells." (PMID 40723282, 2025). "As an oncogene that promotes cell cycle progression, high CCND1 expression is related to increased cancer cell growth and proliferation and decreased cell apoptosis." (PMID 40145254, 2025). "The PI3K/AKT signaling pathway is likely involved in promoting Cyclin D1 upregulation in cancer samples." (PMID 40729351, 2025). "The findings showed that combined therapy induced apoptosis in cancer cells by reducing cyclin D1 and Bcl‐2 expression while improving Bax and caspase‐3 expression." (PMID 40964147, 2025). "They suppress the activity of key regulators like cyclin D1 and cyclin-dependent kinases, which handle cancer cell division." (PMID 40722893, 2025). "The overarching theme across these studies is CREPT’s universal role in promoting G1 phase progression through cyclin D1/CDK4/6 upregulation in various cancers." (PMID 40723282, 2025). "Beyond the recurrent amplification of CCND1, CCND2, CDK4, MDM2, and MYCL1, chromothriptic chromosomes were associated with the amplification or loss of other well-established cancer genes." (PMID 39185963, 2025). "CCND1 itself has the function of repairing damaged DNA, which triggers resistance to chemotherapy drugs and helps cancer cells to rapidly repair damage." (PMID 41305721, 2025). "Amplification and overexpression of Cyclin D1 have been observed in numerous cancer types, including BC and CRC." (PMID 40072047, 2025). "This compound is known to induce cell apoptosis through an intrinsic pathway involving Bax, Bcl-2 and caspase-3 proteins, and it promotes cell cycle arrest by regulating mediators such as cyclin A, cyclin B1 and cyclin D1 in various cancer cells." (PMID 40005281, 2025). "For instance, in cervical cancer, CREPT expression is significantly upregulated in cancer tissues and is positively correlated with cyclin D1 and transcriptional factor 4 (TCF4) expression." (PMID 40723282, 2025).